MTA1 (metastasis associated 1)
Diseases named in the same sentence as MTA1 in open-access papers (continued):
Sharing a sentence is not in itself a finding about the gene and the disease.
prostate intraepithelial neoplasia (2 papers, 2019 to 2025). A neoplastic proliferation of the epithelial cells that line the acini and the ducts of the prostate gland. "We have demonstrated that pterostilbene treatment blocks the progression of prostatic intraepithelial neoplasia and adenocarcinoma in mouse models by inhibiting MTA1 expression and signaling." (PMID 31487842, 2019). "Data showed that pterostilbene treatment inhibited the conversion of high-grade prostate intraepithelial neoplasia (PIN) lesions to cancer by acting through MTA1-mediated signaling to modulate PTEN acetylation, p-Akt/Akt, AR, CyclinD1, NFκB, TGFβ and IL-1β." (PMID 40077738, 2025).
renal cell carcinoma (2 papers, 2020 to 2023). "However, the role of MTA1 in renal cell carcinoma (RCC) progression and metastasis remains unclear." (PMID 33059651, 2020).
salivary gland neoplasm (2 papers, 2016 to 2025). Tumors of the SALIVARY GLANDS. "The present study is the first to evaluate the role of MTA1 in benign and malignant salivary gland neoplasms and compare them with nSGTs." (PMID 26878004, 2016). "High nuclear expression of MTA1 was detected in 83.3% (30/36) of the malignant salivary gland tumors and 45% (9/20) of pleomorphic adenoma, while low MTA1 expression was seen in all of the normal salivary gland tissues." (PMID 26878004, 2016). "In total, 69.6% of normal salivary gland tissues showed MTA1, but all cases of salivary gland tumors were positive for MTA1." (PMID 26878004, 2016).
thymoma (2 papers, 2012 to 2021). A neoplasm arising from the epithelial cells of the thymus. "Compared with early thymoma, advanced thymoma has higher MTA1 levels." (PMID 34620045, 2021). "Therefore, these researchers firmly confirmed that the aggressiveness of thymoma was regulated by the expression of MTA1 gene." (PMID 34620045, 2021).
bladder cancer (1 paper, 2025). "Due to an absence of canine gene expression databases, we searched a publicly available human database for an analysis of the prognostic significance of MTA1 in bladder cancer." (PMID 40351767, 2025).
cataract (1 paper, 2018). Partial or complete opacity of the crystalline lens of one or both eyes that decreases visual acuity and eventually results in blindness. "K14E6 mice cataracts also overexpress MTA1 (mRNA and protein), an effect probably regulated in a TGF-β-dependent manner." (PMID 29888254, 2018). "In particular, MTA1 mRNA and protein also diminish in the K14E6 cataracts." (PMID 29888254, 2018).
colitis (1 paper, 2022). Inflammation of the colon. "Metastasis-associated protein 1 (MTA1), as a chromatin modifier, exerts notable association with multiple diseases, including colitis." (PMID 35764613, 2022). "Initial experimentation illustrated that MTA1 was highly-expressed in DSS-induced experimental colitis mouse models." (PMID 35764613, 2022). "We analyzed the experimental colitis gene expression dataset GSE53835 and found that MTA1 was highly-expressed in experimental colitis." (PMID 35764613, 2022). "The current study aims to investigate the mechanism of MTA1/HIF1A/AQP4 axis in experimental colitis in mice." (PMID 35764613, 2022). "Together, these findings shed a light on involvement of MTA1 in experimental colitis." (PMID 35764613, 2022). "However, the potential and specific mechanism of MTA1 in experimental colitis currently remains elusive." (PMID 35764613, 2022). "In addition, MTA1 facilitated experimental colitis via up-regulating HIF1A." (PMID 35764613, 2022). "Results of dual-luciferase reporter gene assay and ChIP assay further revealed that MTA1 activated HIF1A, and subsequently induced AQP4 transcription to up-regulate AQP4 in experimental colitis." (PMID 35764613, 2022). "Furthermore, analyses of GSE53835 indicated that HIF1A was overexpressed, while co-expression analysis by MEM exhibited that MTA1 and HIF1A were both markedly co-expressed and shared a positive correlation in experimental colitis." (PMID 35764613, 2022). "It was found that MTA1 and HIF1A were both highly-expressed in experimental colitis samples." (PMID 35764613, 2022). "First, experimental colitis mouse models were established using dextran sulfate sodium (DSS) and in vitro colonic epithelial cells FHC inflammation models were with lipopolysaccharide (LPS) for determination of MTA1 and HIF1A expressions." (PMID 35764613, 2022). "Altogether, MTA1 may promote AQP4 transcription by activating HIF1A, thus exacerbating DSS-induced experimental colitis in mice, which provides a novel direction for the treatment of experimental colitis." (PMID 35764613, 2022).
colorectal adenocarcinoma (1 paper, 2020). The most common type of colorectal carcinoma. "On this concept, we built an MTA1-centralized transcriptional coexpression network using RNA-seq data of 382 colorectal adenocarcinoma (COAD) samples from The Cancer Genome Atlas (TCGA)." (PMID 32901005, 2020).
dermatomyositis (1 paper, 2014). Dermatomyositis (DM) is a type of idiopathic inflammatory myopathy characterized by evocative skin lesions and symmetrical proximal muscle weakness. "These complexes contain the dermatomyositis-specific autoantigens, Mi-2α/β, MTA1/2 and p66, which are functionally and physically linked." (PMID 25009653, 2014).
embryonal carcinoma (1 paper, 2022). A non-seminomatous malignant germ cell tumor characterized by the presence of large germ cells with abundant cytoplasm resembling epithelial cells, geographic necrosis, high mitotic activity, and pseudoglandular and pseudopapillary structures formation. "Several studies have shown potential interaction between SOX2 and MTA1/2/3, MBD2, GATAD2A/B, and HDAC1/2 in different cell lines, including embryonic stem cells, neural stem cells, and embryonal carcinoma cells." (PMID 35615634, 2022).
endometriosis (1 paper, 2023). The growth of functional endometrial tissue in anatomic sites outside the uterine body. "Studies in a mouse model of endometriosis further demonstrated that metastasis associated 1 (MTA1) and zinc finger E-box binding homeobox 2 (ZEB2) were up-regulated in ectopic tissues, while polyphenols inhibited ectopic lesion growth and MTA1/ZEB2 expression." (PMID 37375677, 2023).
ependymoma (1 paper, 2016). A WHO grade II, slow growing tumor of children and young adults, usually located intraventricularly. "Poor prognostic features were found in two other patients: low expression of PAX8, FHIT, CASP10, CHD2, with high expression of CHD11, FUS, and MTA1 in a patient with Ewing sarcoma, and gain of 1q and loss of 6q and overexpression of TNC, CALB1, PLAG1, ALDH1L1, and RELN in a patient with ependymoma." (PMID 28007021, 2016).
epithelioid malignant mesothelioma (1 paper, 2015). "We also found MTA1 level in sarcomatoid and biphasic malignant mesotheliomas were higher than the level in epithelioid malignant mesothelioma (p < 0.05)." (PMID 26689197, 2015).
fibrosis (1 paper, 2020). the formation of excess fibrous connective tissue in an organ or tissue in a reparative or reactive process. "Using a combination of in vitro and in vivo studies, we found that MTA1 was significantly up‐regulated in bleomycin‐induced fibrosis rats and TGF‐β1‐treated alveolar type II epithelial (RLE‐6TN) cells." (PMID 32187849, 2020). "To exactly measure MTA1 levels, we performed Western blot and RT‐qPCR analysis and the results revealed that MTA1 was significantly increased in bleomycin‐induced fibrosis, both at protein levels and mRNA levels." (PMID 32187849, 2020).
Goblet cell carcinoids (1 paper, 2009). "Goblet cell carcinoids have increased expression of NAP1L1, MAGE-D2, and MTA-1 genes compared with benign carcinoids." (PMID 19171048, 2009).
HTLV-2 infection (1 paper, 2021). "The majority of samples with untypeable WB results (58.8%, 20/34) had dual reactivity to both K55 and MTA-1 suggestive of dual HTLV-1/HTLV-2 infection as well as to the other Gag proteins (p19, p26, p28, p32, p36)." (PMID 33507996, 2021).
hyperlipidemia (1 paper, 2023). "Our study findings revealed a statistically significant decrease in MTA1 methylation among smokers compared to nonsmokers but found no statistical difference among alcohol drinkers or patients with hyperlipidemia." (PMID 37892177, 2023).
kidney cancer (1 paper, 2020). Primary or metastatic malignant neoplasm involving the kidney. "Furthermore, we showed that MTA1 is up-regulated in ccRCCs, which contributes to the migration and invasion of human kidney cancer cells by mediating the expression of MMP2 and MMP9 through the NF-κB signaling pathway." (PMID 33059651, 2020). "However, the role of MTA1 in kidney cancer and its molecular mechanisms are currently unknown." (PMID 33059651, 2020).
laryngeal squamous cell carcinoma (1 paper, 2014). A squamous cell carcinoma that arises from the larynx. "The function of MTA1 in laryngeal squamous cell carcinoma (LSCC) remains unclear." (PMID 24396455, 2014).
lentivirus infection (1 paper, 2015). Virus diseases caused by the Lentivirus genus. "To further investigate the regulatory effect of ERα, we knocked down ERα in HepG2 cells using shRNA lentivirus infection and observed MTA1 expression." (PMID 26503703, 2015).
liver diseases (1 paper, 2021). "Using the woodchuck model, we studied the complex temporal relationships between MTA1/MTA1dE4 expression and the progression of HBV-related liver diseases, including chronic hepatitis and HBV-HCC." (PMID 34502289, 2021).
lung adenocarcinoma (1 paper, 2026). A carcinoma that arises from the lung and is characterized by the presence of malignant glandular epithelial cells. "Similar correlation and hyperphosphorylation were also observed with MTA1_S576 and CIT_S440 in lung adenocarcinoma datasets." (PMID 41601480, 2026).
malignant pleural mesothelioma (1 paper, 2015). A malignant neoplasm that arises from mesothelial cells in the pleura and shows a diffuse growth pattern. "We aim to investigate the mechanism of MTA1 and metastasis in malignant pleural mesothelioma (MPM)." (PMID 26689197, 2015).
melanoma (1 paper, 2014). A malignant, usually aggressive tumor composed of atypical, neoplastic melanocytes. "MTA1 overexpression is positively correlated with in vitro migration and invasion ability in KYSE150 and B16F10 melanoma cell lines, and inhibition of MTA1 protein expression results in growth inhibition of cancer cell lines." (PMID 24396455, 2014).
osteoporosis (1 paper, 2023). A condition of reduced bone mass, with decreased cortical thickness and a decrease in the number and size of the trabeculae of cancellous bone (but normal chemical composition), resulting in increased fracture incidence. "More importantly, our study may open the way for MTA1 to become a new gene target for osteoporosis research." (PMID 36786127, 2023). "Nonetheless, this study suggests a new hypothesis for the role of MTA1 in osteoporosis." (PMID 36786127, 2023). "However, whether MTA1 affects the development of osteoporosis in preclinical animal models requires further investigation." (PMID 36786127, 2023). "MTA1 may be a potential target for the prevention and treatment of osteoporosis." (PMID 36786127, 2023).
papillary thyroid cancer (1 paper, 2022). "Besides this, circ_MMP2 was determined to advance the progression of papillary thyroid cancer by post-transcriptionally upregulating ABCA9 and metastasis-associated 1 (MTA1)." (PMID 35055115, 2022).
pituitary tumor (1 paper, 2018). A benign or malignant neoplasm affecting the pituitary gland. "It was shown that elevated expression of metastasis-associated gene-1 (MTA1) was linked to the aggressive nature of pituitary tumors." (PMID 29963012, 2018).
pulmonary fibrosis (1 paper, 2020). Chronic progressive interstitial lung disorder characterized by the replacement of the lung tissue by connective tissue, leading to progressive dyspnea, respiratory failure, or right heart failure. "Overexpression of MTA1 promotes lung fibrosis by trigging EMT of alveolar epithelial cells." (PMID 32187849, 2020).
salivary duct carcinoma (1 paper, 2025). An aggressive, high grade adenocarcinoma that arises from the salivary glands. "In the HSG and HSY salivary duct carcinoma cell lines, they discovered that endogenous MTA1 depletion increases ERβ expression." (PMID 40660330, 2025).
salivary gland carcinoma (1 paper, 2025). A carcinoma that arises from the major or minor salivary glands. "The current study aimed to investigate the prognostic relevance of PROX1, and MTA1 in salivary gland carcinomas." (PMID 40660330, 2025). "In a retrospective study on 45 cases diagnosed with salivary gland carcinoma, PROX1 and MTA1 immunoexpressions were assessed concerning the different clinicopathologic parameters, disease-free (DFS), and overall survivals (OS)." (PMID 40660330, 2025).
sarcoma (1 paper, 2014). A usually aggressive malignant neoplasm of the soft tissue or bone. "We selected CCND1, MTA1, STEAP1, CDH2, CDH11, and CDT2 genes that are known to be involved in metastatic spread in several sarcoma subtypes, and their abnormal expression in tumors correlates specifically with poor prognosis in ES patients." (PMID 25008066, 2014).
Sepsis (1 paper, 2025). Sepsis is defined as life-threatening organ dysfunction caused by a dysregulated host response to infection. "DEX could attenuate AKI through KDM5A inhibition in sepsis, transcription and protein levels of genes such as TLR4, MYD88, MTA1, PTGS2, CASP3 associated with NF-κB signaling pathway were all compromising after treated with DEX." (PMID 40989844, 2025).
Stroke (1 paper, 2022). Sudden impairment of blood flow to a part of the brain due to occlusion or rupture of an artery to the brain. "ASHGV40056557 is expressed as NR_037932, which maps to the stroke-associated genes apolipoprotein C and E within 420 kb, while T111838 (ASHGV40056142) maps at 14q32.33 within metastasis-associated protein 1 (MTA1), a transcriptional regulator-associated gene modifing master chromatin." (PMID 35754821, 2022).
testicular cancer (1 paper, 2023). A primary or metastatic malignant neoplasm that affects the testis. "In testicular cancer, an antioxidant cocktail of α-tocopherol, l-ascorbic acid, zinc, and selenium was used to modulate the expression of metastasis-associated protein 1 (MTA1), a gene involved in tumour growth and metastasis." (PMID 36701089, 2023).
urothelial carcinoma (1 paper, 2025). A malignant neoplasm derived from the transitional epithelium of the urinary tract (urinary bladder, ureter, urethra, or renal pelvis). "Although metastasis-associated protein 1 (MTA1) is known to play a role in cancer invasion and metastasis of various cancers, the clinical significance of its expression in canine urothelial carcinoma (UC) has not been explored." (PMID 40351767, 2025).
varicocele (1 paper, 2011). A condition characterized by the dilated tortuous veins of the spermatic cord with a marked left-sided predominance. "Immunoblotting analysis revealed that the expression of MTA1 was decreased in the testes of varicocele patients compared with that in normal group." (PMID 22022494, 2011). "Overall, the expression level of MTA1 in varicocele group (Var) was relatively lower at the low magnification." (PMID 22022494, 2011). "To better understand the pathological relevance of MTA1, therefore, we extended our investigation into the potential involvement of MTA1 in arrested spermatogenesis at the round spermatid level of varicocele." (PMID 22022494, 2011). "Finally, attenuated expression of MTA1 of pachytene spermatocytes was observed in arrested testes (at the round spermatid level) of human varicocele patients." (PMID 22022494, 2011).
vulvar carcinoma (1 paper, 2023). "Conversely, this means that HPV-independent vulvar carcinomas express more MTA1 than HPV-dependent vulvar carcinomas." (PMID 36689059, 2023). "The expression of MTA1 seems to play an important role in the progression of vulvar cancer: advanced vulvar carcinomas are characterized by an increased expression of MTA1." (PMID 36689059, 2023). "Four histological tumor subtypes of vulvar carcinoma were included in this study and examined regarding their expression of MTA1." (PMID 36689059, 2023). "We found a significant upregulation of MTA1 expression in vulvar carcinoma at higher cancer grading as well as higher FIGO stages." (PMID 36689059, 2023). "Nuclear staining of MTA1 resulted in a weak color reaction in 23.8% of the vulvar carcinoma tissue sections (IRS 1–2), 60.3% showed a moderate (IRS 3, 4, 6), and 7.2% a strong color reaction (IRS 8, 12)." (PMID 36689059, 2023). "When classified by the tumor size, presented by the letter T in the TNM classification, a significant upregulation of MTA1 expression in vulvar cancer at higher cancer stages was observed (p = 0.0001)." (PMID 36689059, 2023). "A further examination of a possible downregulation or elimination of MTA1 would represent an interesting therapeutic approach in vulvar cancer." (PMID 36689059, 2023). "A total of 157 paraffin-embedded vulvar cancer tissues were immunohistochemically stained and examined for MTA1 expression by using the immunoreactive score." (PMID 36689059, 2023). "The analyses of the present study clearly show that HPV-independent vulvar carcinomas are characterized by increased MTA1 expression levels, which in turn underlines the importance of MTA1 as a negative prognostic marker for vulvar carcinoma." (PMID 36689059, 2023). "MTA1 was identified as a negative prognostic marker for vulvar carcinoma associated with advanced tumor stage and FIGO grading." (PMID 36689059, 2023). "Therefore, our results support that MTA1 represents a significant factor in tumor progression in vulvar carcinoma and is higher expressed in advanced tumor stages." (PMID 36689059, 2023). "A more detailed investigation of MTA1 and its relation to HPV status in vulvar carcinomas will be the subject of future research." (PMID 36689059, 2023). "Due to the lack of information around MTA1 and its significance regarding vulvar carcinoma, this study focuses on the expression of MTA1 in vulvar carcinoma and its correlation to clinicopathological characteristics and prognosis." (PMID 36689059, 2023). "MTA1 was expressed both in the nucleus and in the cytoplasm in more than 90% of the examined vulvar carcinoma tissue sections, while there was no expression in normal vulvar tissue." (PMID 36689059, 2023). "Since no information about the expression and involvement of MTA1 in vulvar cancer exists to date, we analyzed the expression of MTA1 in tissue samples and its relation to the clinicopathological parameters of the study group." (PMID 36689059, 2023). "The MTA1 staining process in the cytoplasm showed a weak color reaction (IRS 1–2) in 28.6% of the vulvar carcinoma tissue sections, 61.1% showed a moderate color reaction (IRS 3, 4, 6), whereas 4.8% of the specimens showed a strong color reaction (IRS 8, 9, 12) of MTA1." (PMID 36689059, 2023). "In our analyses, the expression of MTA1 was increased in non-keratinized squamous cell carcinoma and vulvar carcinoma of the condylomatous type, although these two tumor subtypes were not simultaneously associated with a worse prognosis in our patient population." (PMID 36689059, 2023). "In addition, p16 negative vulvar carcinomas showed a higher nuclear expression of MTA1 compared to p16 positive vulvar carcinomas." (PMID 36689059, 2023).